DICER1 (dicer 1, ribonuclease III)
Diseases named in the same sentence as DICER1 in open-access papers (continued):
Sharing a sentence is not in itself a finding about the gene and the disease.
cancer (continued). "Nevertheless, Drosha and Dicer1 can also be expressed at higher levels in some cancers, such as in cervical cancer, prostate adenocarcinoma, AML and in precursor lesions of lung adenocarcinoma." (PMID 34722255, 2021). "Full deletion of Dicer1 induces inhibition of tumorigenesis, indicating that cancer cells need a certain minimum level of Dicer expression for tumorigenesis or cell survival." (PMID 34722255, 2021). "The most frequently mutated genes were TNRC6A, DICER1, SMAD4 and ZCCHC11, with mutations in 2–3% of pan-cancer samples." (PMID 33406242, 2021). "Their results suggested that miRNA-107 promotes cancer metastasis through the down-regulation of DICER1." (PMID 32961797, 2020). "The dysregulation of DICER1 that is a principal enzyme in miRNA maturation is also observed in a number of various cancers, while miR-103/miR-107 family has been shown to regulate the expression of DICER1." (PMID 32079166, 2020). "Screening for DICER1 variants should be performed in all patients with PPB and considered in few benign lesions and malignant tumors." (PMID 33552988, 2020). "Specifically, DICER1 mutations containing nonsense and missense variants in one of the four catalytic residues in the RNase IIIB domain (E1705, D1709, D1810, E1813), as we find, are the major known DICER1 events in cancer." (PMID 32455687, 2020). "Global inhibition of miRNA biogenesis by depletion of DICER1 promotes cell growth and tumorigenesis in human cancer cell lines and mouse models of cancer, suggesting the oncogenic role of DICER1 in tumorigenesis." (PMID 32138313, 2020). "The breadth of TCGA and IMPACT sampling across dozens of cancer types allowed us to interrogate potential specificity of DICER1 hotspots." (PMID 31417090, 2019). "This implies there are selective advantages to DICER1 hotspot cancer cells in only certain tissue settings." (PMID 31417090, 2019). "The combination of DROSHA up-regulation and DICER1 down-regulation can initiate accumulation of primary miRNA transcripts and incomplete miRNA maturation, and these can contribute to cancer progression." (PMID 31683635, 2019). "In this study, for the first time, we have comprehensively quantified the prevalence of P/LP germline DICER1 variation in the largest publicly available sporadic adult and pediatric cancer cohorts." (PMID 30672147, 2019). "The expression of AUF1 was markedly increased, while Dicer1 was significantly reduced in the cancer tissues of HCC patients." (PMID 29599909, 2018). "We also identified several cancer-related genes affected by SF3B1-associated abnormal splicing: NF1, PDS5A, DICER1, and PML." (PMID 30194306, 2018). "Estrogen-stimulation of DICER1 activity was neutralized when increasing miR-129 level or inhibiting estrogen receptor expression in cancer stem-like cells." (PMID 29262559, 2017). "We also confirmed the positive correlation between cyclin D1 and DICER1 in cancer cells acquired from N3-treated MCF-7 mammospheres." (PMID 25702703, 2015). "Cyclin D1 was one of the traditional oncogenes in the regulation of cancer malignancy, and more recently, was regarded to miRNA genesis and maturation though regulating DICER1, the key enzyme for miRNAs processing 8,20." (PMID 25702703, 2015). "Previous studies have shown that several types of cancer are associated with alterations to miRNA machinery genes, such as DROSHA, DICER1, XPO5, and AGO2." (PMID 26147304, 2015). "In conclusion, cyclin D1 induces DICER1 and thereby promotes the maturation of let-7 miRNA, and then drive cancer progression in part via miRNA biogenesis." (PMID 25702703, 2015). "We also found that the level of the microRNA-processing enzyme Dicer1 was decreased in the inflammation-cancer link." (PMID 25742789, 2015).
cancer (continued). "In this regard, it has been well documented that one of the key enzymes of the RNAi pathway, Dicer1, has an abnormal expression in different types of cancer, including OSCCs." (PMID 25115815, 2014). "Additional somatic ‘hotspot' mutations in the microRNA processing ribonuclease IIIb (RNase IIIb) domain of DICER1 are reported in cancer, and which affect microRNA biogenesis, resulting in a -3p mature microRNA strand bias." (PMID 24513630, 2014). "A lot of research has been conducted to find out all of DICER1’s functions and how they relate to both cancer-causing and non-cancerous illnesses." (PMID 39857323, 2025). "Genetic analysis showed a compound somatic heterozygous mutation in the DICER1 gene (c.5566G>A and c.4390_4391dup) which is not included in the Catalogue of Somatic Mutations in Cancer (COSMIC)." (PMID 40217628, 2025). "Currently, no specific therapies for cancers and illnesses with mutations in the DICER1 gene have been established and consolidated." (PMID 39857323, 2025). "Now, thyroid blastoma has been newly classified among the DICER1-related malignant tumors." (PMID 40007992, 2025). "In recent years, studies have revealed that DICER1 plays an important role in various cancers." (PMID 40666073, 2025). "Therefore, functional classification of variants that are currently listed as variants of uncertain significance is critically important for a fundamental understanding of DICER1 functions as well as its role in cancer and utility in clinical diagnostics." (PMID 39421690, 2024). "Moreover, it has been shown that miR-130a, through its inhibitory effect on ATG2B and DICER1, inhibits the survival of cancer cells in CLL." (PMID 38473390, 2024). "In addition, different mouse models and human cell lines have been established to study DICER1 effects in cancer by simply knocking out the gene." (PMID 36896180, 2023). "No occurrence of cancer in the mother of the third child presented (despite carrying the same DICER1 gene mutation) can be explained by the methodological limitations of the study." (PMID 37761810, 2023). "For example, genetic aberrations of cancer-associated genes belonging to the miRNA processing protein complex, such as TARBP2, DICER1, and XPO5, are of crucial importance in the cellular transformation pathways and contribute to an overall miRNA dysregulation in cancer." (PMID 38003902, 2023). "The set of 3p miRNAs found to be specifically upregulated in DICER1-driven malignant tumors may be effective markers to discriminate the malignant status of nodules harboring the RNase IIIb mutation." (PMID 36896180, 2023). "We also uncover potential miRNA biomarkers for DICER1-driven malignant tumors that may be valuable in the clinical setting." (PMID 36896180, 2023). "Moreover, we report a patient with bilateral FTC, with the carcinoma on the right lobe harboring biallelic DICER1 alterations (p.G661Vfs*24, p.E1813K) while the carcinoma on the left lobe was DICER1-wt." (PMID 36896180, 2023). "Recent studies have shown that DICER1 is involved in the cancer initiation and development." (PMID 36685857, 2022). "The results showed a similar pattern among cancer genes, oncogenes, TSGs and the whole protein-coding gene population in Dicer1 KO human HCT116 cells, even though the statistical power of our analysis was likely reduced by the lack of biological replications in the NGS analysis." (PMID 35328035, 2022). "DICER1 downregulation represents a prognostic marker of cancer development but the mechanisms at the basis of this phenomenon are still completely unknown." (PMID 35876890, 2022). "However, the reasons for DICER1 downregulation in cancers are not fully understood and represent an emerging open field." (PMID 35876890, 2022).
cancer (continued). "Four biopsy-proven malignant tumors (excluding nonmelanoma skin cancers), identified from the Geisinger Cancer Registry, were observed in the 25 individuals with a DICER1 pLOF variants." (PMID 33630087, 2021). "A comparison of the DICER1 mutations with clinical characteristics of cancers did not reveal any significant associations." (PMID 33406242, 2021). "We identified and characterized over 3600 somatic mutations in 29 miRNA biogenesis genes and showed that some of the genes are overmutated in specific cancers and/or have recurrent hotspot mutations (e.g. SMAD4 in PAAD, COAD and READ; DICER1 in UCEC; PRKRA in OV and LIN28B in SKCM)." (PMID 33406242, 2021). "Furthermore, they reported that overexpression of miRNA-103 in cancer cell lines led to the enhancement of migration or invasion and a significant reduction of DICER1 levels." (PMID 32961797, 2020). "According to this theory, expression of DROSHA and DICER1 might play important roles in the function of specific miRs in human cancers in vivo." (PMID 31214494, 2019). "Thus, although miRNAs are required for normal cell fitness, selective inactivation of DICER1 can benefit cancer cells." (PMID 31417090, 2019). "Thus, the reduced expression of DICER1 appears to be a clinically useful prognostic factor for some cancers." (PMID 29853562, 2018). "While this was not looking into prolactinomas, the pathogenesis of cancer is similar and it demonstrates that the presence of a DICER1 mutation can contribute to pituitary tumorigenesis." (PMID 30306785, 2018). "Consistent with this idea, DICER1 expression is decreased in several types of human cancers." (PMID 26990999, 2016). "These pieces of evidence may reflect the importance of DICER1 on cell survival and/or indicate that a subset of miRNAs is important for cancer progression." (PMID 26990999, 2016). "Besides the contribution by Pten disruption, our studies showed that Dicer1 disruption also contributed to the rapid cell proliferation of the DKO mouse cancer cells." (PMID 27602775, 2016). "In general with few exceptions, cancer cells have decreased global miRNA expression, leading to the hypothesis that upregulation of DICER1 may lead to increased miRNA expression, which would then contribute to lowering tumorigenic activity." (PMID 26990999, 2016). "A recent study indicated that DICER1 functions as a haploinsufficient tumor suppressor in cancer." (PMID 26688807, 2015). "This discrepancy could be explained if DICER1 expression is largely regulated by epigenetic events that suppress translation of DICER1 mRNA in a subset of cancers, leaving transcript levels unchanged." (PMID 23641362, 2013). "Therefore, speeding up the miRNA processing globally or by replacement of Dicer1 in cancer cells can alter their progression and invasive potential." (PMID 22716183, 2012). "The diagnostic workup included hormonal testing, imaging studies, and extensive genetic testing, including DICER1 mutation analysis and multiplex ligation-dependent probe amplification (MLPA), as well as the examination of a next-generation sequencing (NGS) panel covering ~280 cancer-related genes." (PMID 40862798, 2025). "Moreover, pan-cancer studies have identified significant variations in the expression of miRNA-processing genes, including DICER1, DGCR8, and TARBP2, across multiple malignancies, reinforcing the importance of miRNA biogenesis defects in neoplastic progression." (PMID 41463093, 2025). "The patient with pinealoblastoma was also tested for a hereditary cancer panel, including DICER1; however, a predisposing condition could not be detected." (PMID 39860595, 2025).
cancer (continued). "Interestingly, in ALL, overexpression of DICER1 has also been reported, which indicates that, depending on the cancer stage, the DICER1 expression may be affected differently." (PMID 40127989, 2025). "Despite extensive genetic testing, including DICER1 mutation screening and analysis of more than 280 cancer-related genes, no mutations were detected, suggesting that these tumors may have arisen by chance or unknown mechanisms." (PMID 40862798, 2025). "Therefore, our discovery about the regulatory roles of HSP90 and Aha1 in Dicer1 protein expression and miRNA maturation may provide an important mechanistic basis for developing therapeutic approaches toward cancer treatment." (PMID 35736213, 2022). "Therefore, it will be essential to understand if YO-2 targets Dicer1 in cancer cells." (PMID 36612285, 2022). "In this study, we investigated the prevalence of pathogenic DICER1 germline variation in The Cancer Genome Atlas (TCGA; 32 adult cancer types; 9,173 exomes) and the Therapeutically Applicable Research to Generate Effective Treatment (TARGET; two pediatric cancer types; 175 exomes) cohorts." (PMID 30672147, 2019). "In addition, we could not address the question of why miR-98-5p and miR-103/107 regulate different downstream activities by targeting Dicer1 and display different functions in cancer." (PMID 29670086, 2018). "Given that metformin elevates DICER1 in cultured cancer cells, we wanted to examine whether changes in DICER1 expression occur in mice chronically treated with metformin and to compare these findings with those of mice on dietary caloric restriction, an intervention that extends lifespan in mice." (PMID 26990999, 2016). "Finally, it should also be noted that there are many cancers for which neither germline nor somatic DICER1 mutations have a major etiological role." (PMID 25883138, 2015). "Dicer1 and Drosha serve as key regulators of miRNA biogenesis, and alterations in their intracellular levels may contribute to widespread miRNA deregulation in cancers." (PMID 25742789, 2015). "Additionaly, we could not conclude if the loss of DICER1 protein expression has a direct role in cancer progression or is an epiphenomenon reflecting underlying abnormalities." (PMID 26087193, 2015). "Whether certain tRNAs are selectively targeted by DICER1 in cancer in general, and MDS in particular, remains to be seen, but it provides an intriguing hypothesis for the differentially expressed tDRs identified in this study in association with both the diagnosis and prognosis of MDS." (PMID 26400237, 2015). "Evidence indicates that DICER1 may play crucial roles in the tumorigenesis of different cancers." (PMID 26688807, 2015). "Dicer1 inactivation in TAMs (DKO) prompts their immunostimulatory activation, enabling effective immunotherapy in mouse cancer models." (PMID 40475851, 2025). "Interestingly, the distribution of DICER1 hotspot mutations was not even across cancer types." (PMID 31417090, 2019). "The copy number variation of DICER1 and DROSHA correlates well with their expression and survival of NSCLC and other cancer patients." (PMID 26156018, 2015). "The target analysis of miR-202 in HeLa cells revealed two interesting targets, -DICER1 and SKP2, with potential importance in cancer." (PMID 26020509, 2015). "DICER1 mutations are the major cause of familial and nonfamilial PPB, which is a cancer in the lung tissue or pleura of children." (PMID 39963649, 2025).
cancer (continued). "For example, there was an increase in the methylation of an immunologic marker gene CD79A, a decrease in methylation of a tumorigenic modulation gene DICER1, and a decrease in methylation of SLC25A1, a critical gene in mitochondrial homeostasis that is highly upregulated in cancer." (PMID 37138315, 2023). "Although the mechanism by which miRNAs are underexpressed in cancer remains unknown, it could involve the RNAse III-type enzyme DICER1, which plays a fundamental role in processing miRNA precursors to mature miRNAs." (PMID 30967628, 2019). "Analysis of TCGA database using the Cancer Regulome tool showed that the expression of the most highly upregulated miRNAs in PTC—miR-146b-5p, miR-146b-3p, miR-21-3p, miR-21-5p, miR-221-3p, and miR-222-3p—negatively correlated with DICER1 mRNA levels." (PMID 30967628, 2019). "Our results add to the complex picture of the role of DICER1 and DROSHA in cancer." (PMID 26156018, 2015). "Having demonstrated that siDicer1e was capable of suppressing Dicer1e protein levels, but not Dicer1, we next examined the effects of Dicer1e depletion on cancer cell proliferation." (PMID 25115815, 2014). "In support of this hypothesis, a genome-wide search for copy number alterations in cancer has shown frequent duplication of the Argonaute2 (EIF2C2) gene, as well as DICER1 in tumors." (PMID 19557174, 2009). "Therefore, data obtained from cancer specimens only partially recapitulated our findings using the A549 cell line model but clearly support the evidence for the existence of a direct relationship between APE1 and DICER1 expression." (PMID 35876890, 2022). "Thus, there does not appear to be any selective advantage to inactivate DICER1 RNase IIIa in cancer." (PMID 31417090, 2019). "Review of the Cancer Gene Census (COSMIC database) reveals no proto-oncogene in close proximity of either DROSHA or DICER1 that might drive their amplification." (PMID 26156018, 2015). "There is no clear correlation among DICER1 expression, cancer type and disease progression." (PMID 25883138, 2015). "However, the small cohort of carcinomas (only 19 ACCs) did not allow any conclusion about the impact of DICER1 expression in ACC patient survival." (PMID 26087193, 2015). "However, other hypermutated cancers (POLE or MSI) generally lacked DICER1 hotspots." (PMID 31417090, 2019). "In the 235 extracranial solid tumors with histologies not included in prior pediatric pan-cancer analyses, the recurrently altered genes uniquely containing oncogenic alterations (compared to the common tumors) were CTNNB1, DICER1, and NF1." (PMID 38992034, 2024). "Regardless of whether DROSHA and DICER1 are drivers of their amplifications, the amplifications of these two key miRNA biogenesis genes may increase their expression and, as a consequence, may contribute to the global destabilization of miRNA expression observed in many types of cancer." (PMID 26156018, 2015).